OR2M5 (olfactory receptor family 2 subfamily M member 5)
Description:
Odorant receptor.
Synonyms: OR2M5P
Tractability: Antibody: UniProt places it where antibodies can reach, with medium confidence; UniProt predicts a signal peptide or a membrane-spanning region; its Gene Ontology location is reachable by antibodies, with medium confidence.
Gene: Protein-coding gene on chromosome 1 (248,145,148 to 248,146,086, forward strand). Ensembl gene ENSG00000162727.
Subcellular location: Cell membrane
Pathways (Reactome):
Sensory Perception: Expression and translocation of olfactory receptors
Gene Ontology:
Molecular function: olfactory receptor activity; G protein-coupled receptor activity
Biological process: detection of chemical stimulus involved in sensory perception of smell; G protein-coupled receptor signaling pathway
Cellular component: plasma membrane; membrane
Genetic constraint (gnomAD): Loss-of-function variants: 0 observed, 0.47 expected, observed/expected ratio (o/e) 0, 90% interval 0 to 1.84. That is too few expected variants to judge how well the gene tolerates losing a copy. Missense variants: 413 observed, 395.07 expected, observed/expected ratio (o/e) 1.05, 90% interval 0.96 to 1.13. Synonymous variants: 164 observed, 142.18 expected, observed/expected ratio (o/e) 1.15, 90% interval 1.01 to 1.31.
Homologues: Orthologues: chimpanzee OR2M5 (96% identical), dog OR2M9 (78% identical). Paralogues in human: OR2M3 (93% identical), OR2M7 (93% identical), OR2M2 (90% identical), OR2M4 (74% identical), OR2T33 (56% identical), OR2T8 (55% identical), OR2T12 (55% identical), OR2V1 (54% identical), OR2L3 (54% identical), OR2V2 (54% identical), OR2L8 (53% identical), OR2T2 (53% identical), and 80 more.